NLRP1 (NLR family pyrin domain containing 1)
Description:
Acts as the sensor component of the NLRP1 inflammasome, which mediates inflammasome activation in response to various pathogen-associated signals, leading to subsequent pyroptosis. Inflammasomes are supramolecular complexes that assemble in the cytosol in response to pathogens and other damage-associated signals and play critical roles in innate immunity and inflammation. Acts as a recognition receptor (PRR): recognizes specific pathogens and other damage-associated signals, such as cleavage by some human enteroviruses and rhinoviruses, double-stranded RNA, UV-B irradiation, or Val-boroPro inhibitor, and mediates the formation of the inflammasome polymeric complex composed of NLRP1, CASP1 and PYCARD/ASC. In response to pathogen-associated signals, the N-terminal part of NLRP1 is degraded by the proteasome, releasing the cleaved C-terminal part of the protein (NACHT, LRR and PYD domains-containing protein 1, C-terminus), which polymerizes and associates with PYCARD/ASC to initiate the formation of the inflammasome complex: the NLRP1 inflammasome recruits pro-caspase-1 (proCASP1) and promotes caspase-1 (CASP1) activation, which subsequently cleaves and activates inflammatory cytokines IL1B and IL18 and gasdermin-D (GSDMD), leading to pyroptosis. In the absence of GSDMD expression, the NLRP1 inflammasome is able to recruit and activate CASP8, leading to activation of gasdermin-E (GSDME). Activation of NLRP1 inflammasome is also required for HMGB1 secretion; the active cytokines and HMGB1 stimulate inflammatory responses. Binds ATP and shows ATPase activity. Plays an important role in antiviral immunity and inflammation in the human airway epithelium. Specifically recognizes a number of pathogen-associated signals: upon infection by human rhinoviruses 14 and 16 (HRV-14 and HRV-16), NLRP1 is cleaved and activated which triggers NLRP1-dependent inflammasome activation and IL18 secretion. Positive-strand RNA viruses, such as Semliki forest virus and long dsRNA activate the NLRP1 inflammasome, triggering IL1B release in a NLRP1-dependent fashion. Acts as a direct sensor for long dsRNA and thus RNA virus infection. May also be activated by muramyl dipeptide (MDP), a fragment of bacterial peptidoglycan, in a NOD2-dependent manner. The NLRP1 inflammasome is also activated in response to UV-B irradiation causing ribosome collisions: ribosome collisions cause phosphorylation and activation of NLRP1 in a MAP3K20-dependent manner, leading to pyroptosis. [NACHT, LRR and PYD domains-containing protein 1]: Constitutes the precursor of the NLRP1 inflammasome, which mediates autoproteolytic processing within the FIIND domain to generate the N-terminal and C-terminal parts, which are associated non-covalently in absence of pathogens and other damage-associated signals. [NACHT, LRR and PYD domains-containing protein 1, N-terminus]: Regulatory part that prevents formation of the NLRP1 inflammasome: in absence of pathogens and other damage-associated signals, interacts with the C-terminal part of NLRP1 (NACHT, LRR and PYD domains-containing protein 1, C-terminus), preventing activation of the NLRP1 inflammasome. In response to pathogen-associated signals, this part is ubiquitinated and degraded by the proteasome, releasing the cleaved C-terminal part of the protein, which polymerizes and forms the NLRP1 inflammasome. [NACHT, LRR and PYD domains-containing protein 1, C-terminus]: Constitutes the active part of the NLRP1 inflammasome. In absence of pathogens and other damage-associated signals, interacts with the N-terminal part of NLRP1 (NACHT, LRR and PYD domains-containing protein 1, N-terminus), preventing activation of the NLRP1 inflammasome. In response to pathogen-associated signals, the N-terminal part of NLRP1 is degraded by the proteasome, releasing this form, which polymerizes and associates with PYCARD/ASC to form of the NLRP1 inflammasome complex: the NLRP1 inflammasome complex then directly recruits pro-caspase-1 (proCASP1) and promotes caspase-1 (CASP1) activation, leading to gasdermin-D (GSDMD) cleavage and subsequent pyroptosis. [Isoform 2]: It is unclear whether is involved in inflammasome formation. It is not cleaved within the FIIND domain, does not assemble into specks, nor promote IL1B release. However, in an vitro cell-free system, it has been shown to be activated by MDP.
Synonyms: CARD7; DEFCAP; KIAA0926; NAC; NALP1; DKFZp586O1822; CLR17.1; VAMAS1; AIADK; CIDED; DEFCAP-L/S; JRRP; MSPC; PP1044; SLEV1
Tractability: Small molecule: a structure with a bound ligand is known. PROTAC: UniProt records ubiquitination sites on it; ubiquitination databases record sites on it; its protein half-life has been measured; a small molecule that binds it is known.
Gene: Protein-coding gene on chromosome 17 (5,499,415 to 5,619,424, reverse strand). Ensembl gene ENSG00000091592.
Subcellular location: Cytoplasm, cytosol; Cytoplasm; Nucleus; Inflammasome (NACHT, LRR and PYD domains-containing protein 1, C-terminus); Nucleus (NACHT, LRR and PYD domains-containing protein 1, N-terminus)
Subcellular location (Human Protein Atlas): Cytosol; Nucleoplasm
Pathways (Reactome):
Immune System: The NLRP1 inflammasome
Gene Ontology:
Molecular function: ATP binding; ATP hydrolysis activity; cysteine-type endopeptidase activator activity; double-stranded DNA binding; double-stranded RNA binding; enzyme binding; molecular condensate scaffold activity; pattern recognition receptor activity; protein binding; protein domain specific binding; signaling adaptor activity; cysteine-type endopeptidase activator activity involved in apoptotic process
Biological process: antiviral innate immune response; cellular response to UV-B; defense response to virus; neuron apoptotic process; NLRP1 inflammasome complex assembly; positive regulation of inflammatory response; positive regulation of interleukin-1 beta production; protein homooligomerization; pyroptotic inflammatory response; regulation of inflammatory response; self proteolysis; signal transduction; activation of innate immune response; apoptotic process; defense response to bacterium; inflammatory response; intrinsic apoptotic signaling pathway; pattern recognition receptor signaling pathway; response to muramyl dipeptide; canonical inflammasome complex assembly; innate immune response; regulation of apoptotic process
Cellular component: canonical inflammasome complex; cytoplasm; cytosol; NLRP1 inflammasome complex; nucleoplasm; nucleus; NLRP3 inflammasome complex; nucleolus
Genetic constraint (gnomAD): Loss-of-function variants: 93 observed, 132.27 expected, observed/expected ratio (o/e) 0.7, 90% interval 0.59 to 0.83. The upper end of that interval is the gene's LOEUF score, 0.83, which puts it in group 3 of 6, group 1 being the genes least tolerant of losing a copy. Missense variants: 1,515 observed, 1,795.2 expected, observed/expected ratio (o/e) 0.84, 90% interval 0.81 to 0.88. Synonymous variants: 666 observed, 728.79 expected, observed/expected ratio (o/e) 0.91, 90% interval 0.86 to 0.97.
Homologues: Orthologues: chimpanzee NLRP1 (98% identical), macaque NLRP1 (89% identical), dog NLRP1 (57% identical), mouse Nlrp1a (44% identical), rat Nlrp1a (44% identical), rat Nlrp1b (43% identical), mouse Nlrp1b (42% identical). Paralogues in human: NLRP12 (19% identical), NLRP3 (17% identical), NLRP14 (17% identical), NLRP7 (16% identical), NLRP9 (16% identical), NLRP2 (15% identical), NLRP4 (15% identical), NLRP5 (15% identical), NLRP13 (14% identical), NLRC5 (14% identical), NLRP6 (13% identical), NLRP11 (13% identical), and 8 more.
Diseases named in the same sentence as NLRP1 in open-access papers:
NLRP1 is named in the same sentence as 277 diseases in open-access papers, as found by Europe PMC text mining. Sharing a sentence is not in itself a finding about the gene and the disease. The quoted sentences say what the papers report.
vitiligo (53 papers, 2008 to 2025). Generalized well circumscribed patches of leukoderma that are generally distributed over symmetric body locations and is due to autoimmune destruction of melanocytes. "Polymorphisms in the NLRP1 gene significantly contribute to the pathogenesis of vitiligo by promoting inflammatory responses and autoimmune processes that damage melanocytes." (PMID 40837363, 2025). "The CT genotype of the PTPN22 rs2476601 polymorphism is more frequent in vitiligo patients; in the case of the NLRP1 rs2670660 polymorphism it was the AG genotype, and in the TYR rs1393350 polymorphism, it was the AG genotype." (PMID 40837363, 2025). "Our findings were also consistent with the association of NLRP1 overexpression or gain-of-function mutations with the prevalence of skin diseases such as psoriasis, vitiligo, atopic dermatitis or hyperkeratosis where senescence had been widely described." (PMID 38907167, 2024). "NLRP1 variants were first described in association with vitiligo alone or vitiligo-associated multiple autoimmune disease susceptibility." (PMID 38104185, 2023). "It has been confirmed that NLRP1 is associated with a variety of autoimmune diseases, such as enteritis, Addison's disease, vitiligo, type I diabetes, and rheumatoid arthritis." (PMID 37214347, 2023). "Regarding the inflammasome, several polymorphisms in NLRP1 on chromosome 17 were found to be associated with the occurrence of vitiligo." (PMID 37325658, 2023). "Genetic mutations in NLRP1 have been associated with hyperplasia and skin autoimmune disease like vitiligo accompanied with high levels of IL-1β and IL-18 detected in the serum of patients." (PMID 35428946, 2022). "Variations in the NLRP1 gene increase NLRP1 expression, which is a risk factor for the development of inflammatory diseases, including RA, type 1 intrinsic diabetes, vitiligo, and associated autoimmune diseases." (PMID 36387275, 2022). "NLRP1 has been found to be strongly positive in progressing margins of vitiligo and NLRP1 and IL-1β are significantly associated with progressive disease rather than stable vitiligo." (PMID 34768860, 2021). "In humans, specific mutations of NLRP1 gene are related with vitiligo, Addison’s disease, skin inflammation, and cancer susceptibility, but more studies are necessary to shed light into the molecular mechanism of NLRP1 induced pathology." (PMID 33803783, 2021). "A previous study by Levandowski et al45 identified significant NLRP1 haplotype effects associated with vitiligo and other immunologic conditions." (PMID 33378691, 2021). "NLRP1 gain-of-function variants resulting in increased IL-1β secretion have also been associated with susceptibility to vitiligo both in isolation and with an autoimmune and autoinflammatory disease phenotype." (PMID 34258050, 2021). "SNPs (single nucleotide polymorphisms) of NLRP1 are associated with several (auto)inflammatory diseases with a major skin phenotype, such as psoriasis or vitiligo." (PMID 32640751, 2020). "IL-1β level in serum is elevated in patients with vitiligo, and NLRP1 and IL-1β in vitiligo skin are significantly associated with the progression." (PMID 32922182, 2020). "All these results failed to provide strong evidence regarding an association between NLRP1 rs12150220, rs2670660, rs6502867, and vitiligo risk." (PMID 29152150, 2017). "Several studies found an association between NLRP1 and vitiligo, autoimmune thyroid diseases, and type I diabetes." (PMID 29403486, 2017). "Here, we studied the associations between rs12150220, rs2670660, and rs6502867 of NLRP1 gene and the risks of vitiligo or associated autoimmune diseases via meta-analysis." (PMID 29152150, 2017). "The minor T allele of NLRP1 rs12150220 is potentially associated with the reduced risk of vitiligo-associated autoimmune diseases in the Caucasian population, especially SLE, ADD, and TID." (PMID 29152150, 2017).
vitiligo (continued). "Increasing evidence connects the NLRP1 inflammasome to the pathogenesis of skin-associated autoimmune diseases, such as vitiligo, lupus erythematosus, pemphigus vulgaris, and psoriasis." (PMID 28422993, 2017). "For instance, meta-analysis of the association between NLRP1 rs12150220 and vitiligo in the Asian population was performed on just three case-control studies from two articles." (PMID 29152150, 2017). "Variants of NLRP1 proteins have been shown to be associated with vitiligo, an autoimmune disease resulting in areas of skin hypopigmentation as a consequence of melanocytes damage." (PMID 29403486, 2017). "Incongruent conclusions have been reported for the associations of three NLRP1 SNPs (rs12150220, rs2670660, rs6502867) with vitiligo risk." (PMID 29152150, 2017). "Nineteen case-control studies (7,361 cases/28,722 controls) were included for the meta-analysis of the association between NLRP1 rs12150220 and vitiligo-associated autoimmune diseases risk." (PMID 29152150, 2017). "Due to these disparate results, we performed a comprehensive meta-analysis to explore the association between NLRP1 SNPs and vitiligo susceptibility, as well as vitiligo-associated autoimmune diseases." (PMID 29152150, 2017). "We focused on the potential role of NLRP1 variation in the risks of vitiligo and vitiligo-associated autoimmune diseases by systematically identifying all available relevant case-control studies." (PMID 29152150, 2017). "The interplay between NLRP1 gene polymorphisms and other genetic predispositions may also influence the severity and progression of vitiligo." (PMID 40837363, 2025). "Besides, the patients who exhibit variations in CTLA4 or NLRP1, which regulates inflammasome activity, can be identified early as having an increased risk of developing vitiligo." (PMID 40837363, 2025). "Furthermore, L155H and M1184V are two polymorphisms of NLRP1 that will increase the risk for vitiligo disease." (PMID 38644450, 2024). "Similar attenuation was observed for IL-1α and TNFα after LPS stimulation in haplotype 2A patients, which correlates with mutations in the NLRP1 gene that are associated with a high risk of autoimmune diseases, such as vitiligo, Addison’s disease, and type 1 diabetes." (PMID 35069570, 2021). "Furthermore, SNPs in NLRP1 were found to be involved in other diseases, such as vitiligo-associated autoimmune diseases." (PMID 33378691, 2021). "Several different variants of the NLRP1 gene were found to be associated with vitiligo." (PMID 32640751, 2020). "Furthermore, genome-wide association studies suggest that the NLRP1 haplotype appears in autoimmune diseases associated with psoriasis and vitiligo, and has an effect on skin-specific immune responses." (PMID 32312281, 2020). "The rs12150220 polymorphism may attenuate abnormal NLRP1 protein activity or the related inflammation/apoptosis process in the pathogenesis of vitiligo-associated autoimmune diseases." (PMID 29152150, 2017). "Finally, we measured the association between NLRP1 rs2670660/rs12150220 haplotype and the risk of vitiligo-associated autoimmune diseases." (PMID 29152150, 2017). "This meta-analysis demonstrates that within the Caucasian population, the NLRP1 rs12150220 polymorphism may correlate with a decreased risk of vitiligo-associated autoimmune diseases, especially autoimmune Addison's disease, type 1 diabetes, or systemic lupus erythematosus." (PMID 29152150, 2017). "Several studies have described the relevance of variations in the NLRP1 gene in skin diseases such as vitiligo, psoriasis and leprosy, showing that NLRP1 plays a particular role in the skin." (PMID 40555102, 2025). "This is supported by findings that show increased expression of NLRP1 in skin lesions of vitiligo patients, indicating its potential role in the pathophysiological mechanism." (PMID 40837363, 2025).
vitiligo (continued). "Genome-wide association studies (GWAS) have identified approximately 50 vitiligo-susceptibility genes, including PTPN1, PTPN22, NLRP1, FASLG, and TYR." (PMID 40837363, 2025). "For instance, genetic variations of the NLRP1 and NLRP3 inflammasomes have been associated with high levels of IL-1β in the lesions of patients suffering from psoriasis, vitiligo, and atopic dermatitis." (PMID 38068996, 2023). "Nuclear localized leucine-rich repeat protein 1 (NLRP1), a member of the NOD-like receptor family, is considered to be an innate immune-modulator associated with vitiligo." (PMID 37737154, 2023). "NLRP1 and IL-1β protein expression was strongly positive in perilesional skin of vitiligo patients with disease progression, particularly in the entire epidermis, compared to skin of healthy controls." (PMID 37325658, 2023). "In another study, higher expression of NLRP1 protein in leading edge vitiligo skin biopsies compared to healthy control skin were found, however, NLRP1 was almost exclusively detected in Langerhans cells." (PMID 37325658, 2023). "And the positional cloning of the 17p13 region identified the NLRP1 gene as the likely source of the vitiligo linkage signal." (PMID 35643735, 2022). "NLRP-1 (nuclear localization leucine-rich-repeat protein 1) is another component of innate immunity identified in vitiligo." (PMID 35643735, 2022). "Candidate gene studies highlight the role of autoimmunity in vitiligo, as polymorphisms in IL1B, IL4, PSMB8, NLRP1, NPY, FOXP3, and IFNG genes were found to be associated with vitiligo." (PMID 36164321, 2022). "In this review, from the perspective of activators and inhibitors, we collected evidence from the widely-studied inflammasomes, NLRP3, AIM2, and NLRP1, in psoriasis, vitiligo, SLE, and AD." (PMID 32528469, 2020). "By detecting NLRP1 markers, it can not only monitor the infiltration of inflammation during the progression of vitiligo, but also effectively assess the activity of the disease." (PMID 32922182, 2020). "Given the fact of insufficient statistical power more data was needed to confirm these statements, and further determine the role of NLRP1 SNPs in the presence of vitiligo, or vitiligo together with autoimmune diseases." (PMID 29152150, 2017). "In the context of vitiligo, aberrant activation of the NLRP1 inflammasome may trigger an autoimmune response against melanocytes." (PMID 40837363, 2025). "Moreover, numerous auto-inflammatory diseases connect with increases in NLRP1 inflammasome activity due to dysregulation of NLRP1, including vitiligo, systemic sclerosis, melanoma and Addison’s disease." (PMID 38644450, 2024). "Single nucleotide polymorphisms (SNPs) of the NLRP1 gene are associated with different (auto)inflammatory diseases, which mainly affect the skin, including vitiligo, Addison’s disease, and NAIAD (NLRP1-associated autoinflammation with arthritis and dyskeratosis)." (PMID 36293159, 2022). "Inhibition of NLRP1 might be effective for patients suffering from inflammatory skin conditions such as vitiligo or psoriasis." (PMID 32640751, 2020). "Two studies reported that NLRP1 levels were upregulated in both melanocytes and keratinocytes at the edge of progressing vitiligo lesions, which suggested that the NLRP1 inflammasome might drive the disease via two pathways." (PMID 32528469, 2020). "In humans, DDR1, XBP1, NLRP1 and PTPN22 genes have been linked to vitiligo and these genes could be a starting point to investigate if animals with vitiligo are linked to the genes and mutations reported in humans." (PMID 31324191, 2019). "Interestingly, it has also been shown that different autoimmune diseases, like vitiligo and systematic lupus erythematosus (SLE) are associated with defects in NLRP1." (PMID 31601004, 2019).